DCAF8-DT (DCAF8 divergent transcript)
Gene: Long non-coding RNA gene on chromosome 1 (160,261,682 to 160,281,935, forward strand). Ensembl gene ENSG00000228606.
Gene Ontology:
Biological process: SRP-dependent cotranslational protein targeting to membrane, signal sequence recognition
Cellular component: signal recognition particle, endoplasmic reticulum targeting